IL17A (interleukin 17A)
Diseases named in the same sentence as IL17A in open-access papers (continued):
Sharing a sentence is not in itself a finding about the gene and the disease.
lung cancer (continued). "And it was found that IL-17A stimulation can promote the invasion and migration of lung cancer cells in vitro." (PMID 36349316, 2022). "As a representative factor of adaptive immunity, the role of interleukin-17A (IL-17A) in lung cancer is still unclear." (PMID 36349316, 2022). "Other researchers reported that PM2.5 upregulated Wnt3a/β‐catenin pathway and IL-17a signal pathway or reduced the levels of 15-lipoxygenases, which influenced the progression of lung cancer." (PMID 36496421, 2022). "The mechanisms regarding IL‐17A in PF, inflammation, or lung cancer include a variety of signalling pathways, such as TGF‐β, PD‐1/STAT3, JAK2, and NF‐κB signalling." (PMID 36308405, 2022). "The lung cancer microbiome promotes immunosuppression of lung cancer by inducing IL-17A production by γδT cells." (PMID 36358736, 2022). "The expression of IL-17A in human lung cancer specimens is positively correlated with tumour microvessel and lymphatic vessel density, and it facilitates tumour metastasis." (PMID 36349316, 2022). "For example, IL‐17A was shown to be either protumorigenic or anti‐tumorigenic in different non‐small cell lung cancer (NSCLC) models." (PMID 34570961, 2021). "To characterize Th17 cells in lung cancer, we established a urethane‐induced lung cancer model in IL‐17A‐EGFP transgenic mice and isolated cells from lung cancer lesions." (PMID 34570961, 2021). "Local suppression of IL-17a in the lung of a model with lung cancer showed improved anti-tumor immunity featured by the enhanced IFNγ, a reduced number of T-regulatory cell and the inhibited tumor growth." (PMID 32554855, 2020). "RT-qPCR and western blotting analysis also demonstrated that IL-17a expression levels were higher in lung cancer samples compared to the adjacent normal tissues." (PMID 32554855, 2020). "In order to further confirm the significant role of IL-17a regulated by PM2.5 in pulmonary progression and lung cancer development, IL-17a knockout (IL-17a-/-) mice were used subsequently." (PMID 32554855, 2020). "An obvious up-regulation of IL-17a in the lung cancer tissues compared to the normal tissues was detected by IHC staining, and IL-17a expression was found to be positively correlated with lung cancer progression." (PMID 32554855, 2020). "Targeting of IL‐17A derived from Th17 cells is beneficial in experimental lung cancer by inhibiting lung tumor‐infiltrating T regulatory cells and inducing IFN‐γ‐producing CD4+ T cells in the presence of T‐bet." (PMID 31903715, 2020). "Consistently with previously reported findings, the present study demonstrated the beneficial role of IL‐17A derived from γδT cells in tumor surveillance for lung cancer." (PMID 31903715, 2020). "In lung cancer cells, increased levels of IL-17A and PGE2 were involved in the development of an M2-macrophage-dominant tumor microenvironment." (PMID 32987705, 2020). "IL-17A has been shown to promote tumorigenesis in the absence and presence of NTHi-induced inflammation in a Kras-dependent lung cancer model." (PMID 31316109, 2019). "Considering the finding showing that NF-κB activation is required to IL-17A mediated EMT in lung cancer, we next investigated that eventuality in LSCC." (PMID 31885577, 2019). "Inhibition of IL-17A augments the cytotoxicity of tumor-infiltrating lymphocytes and contributes to tumor suppression in colon cancer and lung cancer in mice." (PMID 27935862, 2017). "IL-17A effects on growth and metastasis of lung cancer cells has also been explored in animal models of development of disease." (PMID 28715437, 2017). "We observed a higher median concentration of IL-17A in the lung cancer milieu when compared to opposite lung and PB." (PMID 27866241, 2017). "An induction of IL-17A mRNA and protein expression was noted in lung CD4+ T cells in patients with NSCLC as compared to healthy controls, suggesting IL-17 is involved in lung cancer." (PMID 24872958, 2014).
lung cancer (continued). "This review updates current understandings on the effect of the cytokines TGF-β, IL-10, and IL-17A on the lung immune responses to antigen, and analyzes their involvement in allergic asthma and lung cancer." (PMID 22855687, 2012). "Similarly, in lung cancer, cytokines have a significant impact on cancer prognosis, such as the upregulation of IL-17A in the lung tumor-induced overexpression of NLRP3 and the enhanced lung tumor invasiveness ability mediated by the EMT." (PMID 39941895, 2025). "IL-17A is reportedly involved in lung cancer inflammation and PD-1 checkpoint blockade therapy." (PMID 41254689, 2025). "However, IL-17A was found to play a protective function in the development of lung cancer in a mouse study that used a different hereditary lung tumor model." (PMID 40370457, 2025). "For instance, overexpression of PD‐L1 induced by the aryl hydrocarbon receptor in non–small cell lung cancer reduces the efficacy of anti‐PD‐1 treatment; IL‐17A increases PD‐L1 expression via the p65/NRF1/miR‐15b‐5p axis, promoting resistance of CRC to PD‐1 antibody therapy." (PMID 39503247, 2024). "According to these findings, we show here that IL-17A affects cell apoptosis together with cellular events associated with DNA damage and genomic instability, supporting the concept that IL-17 could play an important role in the development of lung cancer." (PMID 38999871, 2024). "Additionally, the relationship between IL-17A and ferulic acid 4-sulfate levels and LUAD risk can be evaluated to develop lung cancer risk prediction models and targeted intervention strategies based on these two factors." (PMID 39257908, 2024). "Moreover, previous studies on the relationship between IL-17A and lung cancer have yielded contradictory results." (PMID 39257908, 2024). "Considering the promoting effect of IL-17A on the invasion and metastasis of lung cancer, targeted therapy with IL-17A may inhibit both tumorigenesis and bone destruction." (PMID 38394046, 2024). "For example, IL-17A has been shown to facilitate cell invasion of lung cancer." (PMID 38430256, 2024). "Macrophages could synthesize IL-17A and IL-17F, and in turn, IL-17A and IL-17F promoted lung cancer cell growth by macrophages." (PMID 37581321, 2024). "We examined whether IL-17A derived from lung cancer cells affects osteoclast differentiation by regulating OCP apoptosis." (PMID 38394046, 2024). "Considering the correlation between IL-17A and poor prognosis of patients with tumors and the effect of IL-17A on osteoclastogenesis, we used RAW264.7 cells and an animal model of BM to assess the effect of IL-17A isolated from lung cancer cells on osteoclastogenesis and its underlying mechanisms." (PMID 38394046, 2024). "In vitro, IL-17A promotes lung cancer cell migration, invasion and colony formation ability." (PMID 37978543, 2023). "The relationship between IL-17A and autophagy in lung cancer cells has been rarely studied." (PMID 37978543, 2023). "Over the past decade, multiple lines of evidence have suggested that IL-17A/Th17 may play an oncogenic role in lung cancer." (PMID 37444399, 2023). "The experimental results suggested that endogenous IL-17A could stably promote lung cancer cell migration, invasion and EMT, while knockdown of IL-17A significantly decreased these abilities of tumor cells." (PMID 37978543, 2023). "First, we detected the expression of IL-17A in lung cancer tissues and adjacent tissues." (PMID 36349316, 2022). "IL-17A/F could manipulate immune cells such as macrophages leading to progression of lung cancer cell growth." (PMID 35603223, 2022). "Therefore, understanding the mechanism of IL-17A in lung cancer can provide more options for its treatment." (PMID 36349316, 2022). "The effect of IL-17A on lung cancer is not yet fully understood." (PMID 36349316, 2022). "In vitro studies have also reported that IL-17A have tumour-promoting effects in lung cancer." (PMID 36349316, 2022).
lung cancer (continued). "IL-17A could influence the transcriptional activity of NFAT and trigger the stimulation of T lymphocytes cells, which might increase risk of lung cancer." (PMID 36300118, 2022). "Together, findings above indicated that PM2.5 exposure could promote IL-17a expression, which might be involved in the initiation and progression of lung cancer." (PMID 32554855, 2020). "Taken together, these data revealed that PM2.5 could promote the progression of lung cancer by enhancing the proliferation and metastasis through IL-17a signaling." (PMID 32554855, 2020). "Furthermore, lung carcinogens are highly inflammatory and studies in Tunisia, for example, identified alterations in inflammatory genes- TNF-α, IL8, IL17A, IL17F, CCR2, and VDR Fok1 (rs2228570) and ApaI (rs7975232) that predispose to lung cancer." (PMID 33659210, 2020). "Taken together, all these results expanded the understanding of pulmonary carcinogenesis of PM2.5 through increasing IL-17a expression levels, and thus IL-17a could be a biomarker for lung cancer prediction under the stress of PM2.5." (PMID 32554855, 2020). "Multiple lines of evidence suggest that IL17A/Th17 may play a pro-tumorigenic role as an increased number of Th17 cells are found in human colorectal, gastric, hepatocellular, and lung cancers." (PMID 31921642, 2019). "Considering that IL-17A has been shown to mediate EMT in lung cancer and that IL17/Th17 cells would accompany LSCC development, we next evaluated the profile expression of IL-17A which may prevail to EMT dependent LSCC invasiveness." (PMID 31885577, 2019). "However, there is increasing evidence that IL-17A plays an important role in the pathogenesis of allergic asthma and lung cancer." (PMID 22855687, 2012). "However, other studies have reported that IL-17A can inhibit lung cancer growth and angiogenesis." (PMID 39257908, 2024). "However, it is unclear whether IL-17A derived from lung cancer cells affects osteoclastogenesis by regulating OCP apoptosis." (PMID 38394046, 2024). "Precise targeting IL-17A may efficiently modulate PD-L1 expression in lung cancer cells." (PMID 37978543, 2023). "Therefore, we hypothesize that the efficacy of immune checkpoint inhibitors may be compromised in lung cancer patients with AID following the use of IL-17A monoclonal antibody." (PMID 37978543, 2023). "Therefore, in recent years, IL-17A has been studied in a variety of preclinical lung cancer models." (PMID 35883573, 2022). "In addition, it has been reported that inhibition of IL-17A could enhance the anti-tumor immune response in melanoma and lung cancer; thus, it is possible that targeting of IL-17A suppresses tumor growth in ER-positive breast cancer." (PMID 27935862, 2017). "Therefore, anti-IL-17A treatment strategies could provide an attractive approach to lung cancer therapy." (PMID 22855687, 2012). "In lung cancer, the protein BTNL2 further suppresses antitumor immunity by enhancing IL-17A production and recruiting myeloid-derived suppressor cells." (PMID 40536951, 2026). "Recent research reports that IL‐17A activates the NLRP3 inflammasome, which mediates the EMT process in lung cancer." (PMID 39092293, 2024). "Herein, we observed that expressions of IL-17A and its receptor, IL-17 receptor C (IL-17RC), were elevated in LUAD tissues and were correlated with poor survival in different lung cancer cohorts." (PMID 37444399, 2023). "It was reported that under the stimulation of IL‐17A, the process of migration, invasion, and EMT can be promoted by NLRP3 activation in lung cancer." (PMID 37062076, 2023). "It was found that after blocking NLRP3, the effects above after IL-17A stimulation was weakened, confirming that IL-17A can promote the migration, invasion and the EMT process of lung cancer cells by activating NLRP3 in vitro." (PMID 36349316, 2022). "Therefore, IL-17a might play a promotional role in PM2.5-induced progression of lung cancer." (PMID 32554855, 2020).
lung cancer (continued). "The levels of Th17 markers, such as RORC2, RORα4, IL-17A, IL-17A receptor, and VEGF, were significantly elevated in lung cancer patients, and immune effector T cells (Teff) from small cell lung cancer (SCLC) patients included a large population of Th17 cells." (PMID 32203101, 2020). "High expression of the BC-specific ICD-derived metagene signature (TNF/CXCR3/P2RX7/CASP1/NLRP3/IL1B/LY96/CD4+/CD8+A/CD8+B/PRF1/IFNG/IL17A/IL17RA) is associated with prolonged overall survival (OS) in BC and OC patients but not in lung cancer patients." (PMID 37445860, 2023). "Pairwise comparison unfolded a significant increase of IL-17A in patients with ICIaP compared to lung cancer (p = 0.011) and to ILD other than ICIaP (0.004) but not to healthy controls (p = 1.000), whereas IFN-γ showed no significance in pairwise comparison with ICIaP." (PMID 34347128, 2022). "However, to date, there has been no relevant research on the role of NLRP3 in lung cancer cells stimulated by IL-17A." (PMID 36349316, 2022). "Similarly, IL-17A was significantly increased in patients with ICIaP compared to lung cancer and ILD, but not compared to healthy controls." (PMID 34347128, 2022). "The limitation of our research is that we did not carry out in vivo experiments, which could not well reflect the true effect of IL-17A on lung cancer in vivo." (PMID 36349316, 2022). "Here in our study, the markedly increased expression of IL-17a was detected in lung tissues, peripheral blood lymphocytes and splenic lymphocytes of mice with long-term PM2.5 exposure, further demonstrating the potential of PM2.5 in inducing lung cancer by increasing IL-17a expression levels." (PMID 32554855, 2020). "In conclusion, we found that IL-17A promotes the migration, invasion and the EMT process of lung cancer cells in vitro without affecting cell proliferation, and this process was accompanied by NLRP3 activation." (PMID 36349316, 2022). "The significance of IL-17A, CRP and IL-6 suggests that not just Th-2 or Th-17 cells are important in lung cancer progression and supports our hypothesis that the inclusion of a broader cytokine panel can capture the multi-faceted role of inflammation in lung cancer." (PMID 28402963, 2017).
depression (169 papers, 2012 to 2026). "IL-17A causes depression-like symptoms by increasing the NF-κB and p38MAPK signaling in different brain regions in mice." (PMID 40698360, 2025). "Several studies have linked the IL-17A and IL-23A pathways to anxiety and depression in both human subjects and animal models." (PMID 38956309, 2024). "Recent studies have also identified the role of IL-17A and more pathogenic and inflammatory T-helper cell 17 type (Th17) subpopulations in depression, especially treatment-resistant depression." (PMID 38067176, 2023). "For example, increased tumor necrosis factor-α (TNF‐α) and interleukin (IL)‐1β, IL-6, and IL-17A are linked to the occurrence of anxiety and depression in coronary heart disease patients." (PMID 37878890, 2023). "Similar to psoriasis and MS surveys, patients with rheumatoid arthritis who have elevated levels of IL-17A also have an increased risk of depression and anxiety disorders." (PMID 35935951, 2022). "From the pathological perspective, IL-17A has been implicated in the pathogenesis of autoimmune diseases, obesity-associated chronic low-grade inflammation, tumorigenesis, neurodegeneration, depression, and autism." (PMID 36614020, 2022). "A population-based cohort study found that patients with Ps who have elevated levels of IL-17A also have increased risk for depression and anxiety disorders." (PMID 34367160, 2021). "In a murine imiquimod model of psoriatic disease, administration of IL-17A was associated with acceleration of depression-like symptoms, while treatment with an anti-IL17A antibody diminished depression-like symptomatology." (PMID 34367160, 2021). "Two studies with animal models have also demonstrated that increased levels of IL-17A are associated with depression-like behaviors." (PMID 30400354, 2018). "IL-17A released from different immune cells may be responsible for the development of neuropsychiatric symptoms associated with depression." (PMID 40698360, 2025). "IL-17A levels are associated with cognitive evaluations in late-life depression." (PMID 39655201, 2024). "Thus, theauthors concluded that IL-17A plays an essential role in comorbid depression associatedwith psoriatic inflammation, where both NFκB and p38 MAPK pathways are involved via theupregulation of inflammatory mediators in the brain." (PMID 34819201, 2021). "Thus, the excessive release of IL-17A and the binding with IL-17Rc in microglia and astrocytes may further trigger neuroinflammation, thereby causing depression." (PMID 36430328, 2022). "Other studies have reported an elevation in the levels of Th17 cells in the peripheral blood and serum IL-17A in patients with depression compared to healthy controls." (PMID 40469524, 2025). "Microglia, upon IL-17A stimulation, adopt pro-inflammatory phenotypes that promote neuronal injury in models of AD and depression." (PMID 40469524, 2025). "It was confirmed that anti-IL-17A antibodies prevent the development of depression and decrease the severity of somatic symptoms after treatment withdrawal." (PMID 40141110, 2025). "In psoriasis patients with co-occurring depression, neutralizing antibodies that target Th17 cells (anti-IL-17A, Ixekizumab; anti-IL-12/IL-23, Ustekinumab) have shown promising benefits." (PMID 39655201, 2024). "Postpartum women, elderly gastric cancer patients, acute ischemic stroke patients, and multiple sclerosis patients with depression have elevated Th17 cells and IL-17A." (PMID 39655201, 2024). "Depression promoted the proliferation and activation of Th17 cells, thereby exacerbating the inflammatory response and producing the inflammatory cytokine IL-17A." (PMID 39720595, 2024). "Recently, the effect of Th17 cells and IL‐17A in depression has been investigated, which is obviously augmented in the peripheral circulation of depression patients." (PMID 39660880, 2024).